MPO (myeloperoxidase)
Diseases named in the same sentence as MPO in open-access papers (continued):
Sharing a sentence is not in itself a finding about the gene and the disease.
Arthritis (65 papers, 2011 to 2025). Inflammation of a joint. "Regarding the generation of NETs, and consequently, the high level of MPO in both plasma and synovia of RA patients, depletion of MPO was considered in a mouse model with arthritis, and the result was associated with a reduction of the disease severity." (PMID 35626700, 2022). "The first larger epidemiological study compared 92 cases of MPO deficient individuals to a matched control group and revealed an association of MPO deficiency with increased occurrence of infectious complications and higher prevalence of chronic inflammatory disease, specifically arthritis." (PMID 33916434, 2021). "In line with this, we demonstrated that local levels of MPO were abundantly present and strongly reduced with IL-7R blockade, indicating that IL-7R-induced T-cell activation and increased arthritis are associated with increased granulocyte activity in the inflamed joints." (PMID 22676399, 2012). "In RA, the increase in ROS levels during inflammation and arthritis is partly due to the release of myeloperoxidase from activated neutrophils." (PMID 40342737, 2025). "They found that MPO contributes to the development of arthritis: MPO enhanced the proliferation and decreased the apoptosis of synovial fibroblasts in vitro." (PMID 39199167, 2024). "There are indications that products derived from NETs (vide infra) such as citrullinated histone H3 (H3Cit), cell-free DNA and MPO play a major role in arthritis and diagnosis." (PMID 39199167, 2024). "Acetate reduced arthritis severity in collagen-induced arthritis (CIA) mice, which was associated with a decrease in the articular neutrophils and the myeloperoxidase-deoxyribonucleic acid complex in serum." (PMID 37884797, 2023). "The mechanical pain threshold, volume of the hind paws, and grip endurance, as well as clinical appearance, myeloperoxidase activity, rate of plasma extravasation, and histological signs of arthritis in the ankle joints, were evaluated." (PMID 35745590, 2022). "MPO activity of the hind paws was detected using luminescent imaging of luminol 2 and 6 days after the initiation of arthritis." (PMID 35745590, 2022). "Our present study demonstrated increased synovial tissue levels of XOR and NT in both arthritis study groups compared to healthy controls, while MPO was elevated only in RA patients." (PMID 35886901, 2022). "Arthritis was characterized by mechanical hyperalgesia, paw swelling, movement range of the ankle joint, hanging performance, plasma extravasation rate, myeloperoxidase activity, and histological changes in the tibiotarsal joint." (PMID 35745590, 2022). "MPO has been identified in the synovial fluid of OA and RA patients, and intra-articular injection of MPO has been documented to increase arthritis severity in mouse models." (PMID 34299030, 2021). "In a CFA-induced arthritis model, Trpa1-/- mice exhibited reduced arthritis symptoms and myeloperoxidase activity, as a reflex of neutrophil activation, in the ankle joints." (PMID 34768891, 2021). "In two prominent mouse models of RA, namely K/BxN antibody-mediated arthritis and collagen-induced arthritis, a specific role for MPO was indicated by reduced disease severity in MPO−/− mice." (PMID 32899436, 2020). "Genetic lack of sst4 receptors did not alter mechanical hyperalgesia, edema formation, hanging performance, arthritis score, plasma extravasation, or myeloperoxidase activity." (PMID 31551776, 2019). "MPO was increased by arthritis induction, and this effect was significantly reduced by the highest dose of osteostatin." (PMID 31394717, 2019). "Arthritis induction increased the activity of plasma MPO (+400%) and globulins (+30%) while it decreased the levels of albumin (−44%) and the albumin/globulin ratio (−60%)." (PMID 30210649, 2018). "MPO activity, a biochemical index of granulocyte infiltration, increased in the joint cavity exudate 7 days after induction of arthritis, when compared to control animals." (PMID 28587618, 2017).
Arthritis (continued). "Using Lysm-eGFP mice, which present eGFP-expressing neutrophils, we showed an increase in the neutrophil accumulation in the adipose tissue at 24 hours and in the liver at 3 and 24 hours following arthritis induction, concurring with the MPO data." (PMID 26742100, 2016). "Luminol bioluminescence imaging showing MPO activity in the inflamed joints of PACAP+/+ mice peaked in the initial phase of arthritis, reaching a maximum on day 1 and gradually decreasing thereafter." (PMID 25048575, 2014). "After 40 days of the primary induction of arthritis, the MPO level was elevated in the joints of mice with CIA-mice." (PMID 25375820, 2014). "Myeloperoxidase activity in the ankle joints of PACAP−/− mice was significantly reduced in the early phase of arthritis, but increased in the late phase." (PMID 25048575, 2014). "The induction of arthritis resulted in a significant enhancement in myeloperoxidase activity with respect to the corresponding naïve animals, in HO-1+/+ and HO-1+/− mice but not in HO-1−/− mice." (PMID 23285041, 2012). "Based on these observations and related studies, we hypothesize that exosomal LCN2 and MPO derived from neutrophils may promote RA joint injury, while TP may alleviate arthritis symptoms of CIA rats by blocking this effect." (PMID 38888462, 2024). "The change of serum MPO–DNA levels may reflect the changes of both skin lesion and arthritis, whereas the change of traditional parameters can only mirror the change of one aspect of PsA." (PMID 35774788, 2022). "Surprisingly, the lack of MPO or its inhibition elevates T cell responses in lymph nodes, causing enhanced skin delayed-type hypersensitivity and antigen-induced arthri-tis." (PMID 33916434, 2021). "The delayed decrease of MPO-activity has previously also been observed in the K/BxN serum transfer model, where mice deficient in PACAP, a major vasoactive peptide mediator, showed a similarly increased neutrophil ROS production in the late phase of arthritis." (PMID 30509328, 2018). "However, its effect on neutrophil ROS production follows an interesting biphasic pattern, demonstrated by MPO activity that is lower in the early, but higher in the late phase of arthritis." (PMID 30509328, 2018). "Similarly to what we found in this arthritis model, elevated MPO-levels in RTX-desensitized mice were previously detected in LPS-induced acute airway inflammation." (PMID 25524130, 2015). "Indeed, we found that treatment of ~3-week-old c1LysMcrec2−/−and c1LysMcrex−/−c2−/− mice with neutralizing TNF antibody reduced clinical manifestations including, clinical arthritis and neutrophil MPO activity in limbs." (PMID 25693118, 2015). "Since chloride ions are substrates of MPO, reducing the intake of salt may have positive effects for arthritis patients: it was suggested that increased bone erosion under high-salt conditions can be attributed to an enhanced oxidative milieu maintained by infiltrating neutrophils." (PMID 39199167, 2024). "Furthermore, MPO can activate inflammatory cells and induce the production of inflammatory mediators, including cytokines and chemotactic factors, thereby intensifying the inflammatory response in arthritis." (PMID 39554315, 2024). "Interleukin-6 (IL-6), tumour necrosis factor-alpha (TNF-α), and myeloperoxidase (MPO) play crucial roles in the pathology of various diseases, particularly arthritis and autoimmune conditions." (PMID 39125536, 2024). "Recent research has demonstrated that treatment with naringenin after the onset of collagen-induced arthritis can alleviate arthritis symptoms by modulating the levels of the cytokines IFN-γ and IL-17, myeloperoxidase, nitric oxide, and C-reactive protein." (PMID 39086864, 2024). "A considerable reduction in MPO enzyme activity and MDA level, as well as an increase in SOD enzyme activity and GSH level, was noticed in the ankle joint tissue of mice with arthritis after oral gavage administration of glucosamine sulfate and the AKK PROBIO." (PMID 39479687, 2024).
Arthritis (continued). "Upon administering glucosamine sulfate and the LR‐AFY02 strain via oral gavage, a notable decrease in MPO enzyme activity and MDA level, along with an increase in SOD enzyme activity and GSH level, was observed in the ankle joint tissue of mice with arthritis." (PMID 39554315, 2024). "For example, MPO knockout mice exhibited an enhanced response of CD4+ T cells in lymph nodes, aggravating arthritis." (PMID 35912260, 2022). "In MSU crystal-induced arthritis mouse models pretreated with HSP60 vivo-morpholino, paw swelling, myeloperoxidase (MPO) activity, and inflammatory cell infiltration significantly decreased." (PMID 33488933, 2020). "After injection with complete Freund's adjuvant, body weight, arthritis score, and the serum levels of TNF-α, IL-1β, IL-6, myeloperoxidase (MPO), malondialdehyde (MDA), superoxide dismutase (SOD), and glutathione peroxidase (GSH-PX) were assessed." (PMID 28491105, 2017). "In RTX-pretreated mice, the autoantibody-induced joint swelling, arthritis severity score, MMP and MPO activities, as well as histopathological alterations were significantly greater compared to non-pretreated animals." (PMID 25524130, 2015). "Luminol-derived bioluminescence showed a significant increase in neutrophil MPO activity in the ipsilateral hind paws of all CFA-injected rats 2 days after arthritis induction compared to that of the respective non-arthritic controls." (PMID 38542266, 2024). "TRPA1 WT and KO mice with serum transfer arthritis showed elevated MPO activity 2 and 6 days after challenge irrespective of vehicle or DMTS treatment compared to the baseline enzyme activity." (PMID 35745590, 2022). "Plasma leakage and keratinocyte chemoattractant production in the tibiotarsal joint, but not myeloperoxidase activity was significantly reduced by SzV-1287 in K/BxN-arthritis." (PMID 28067251, 2017). "Although not specifically in PsA, in the context of arthritis, MPO has been shown to be elevated in SF and serum derived from RA patients, and has been linked to the maintenance of oxidative stress in both psoriasis and RA." (PMID 25097465, 2014). "However, we did not observe any significant differences in clinical arthritis scores, MPO activity, or inflammatory cell infiltration among the control, ARB-treated, or ACEi-treated groups." (PMID 37907743, 2023). "Mice undergoing K/BxN serum-transfer arthritis and lacking functional TRPA1 receptors showed more severe mechanical hyperalgesia, more expressed plasma extravasation, and MPO activity in the inflamed limb, as well as increased MIP-2 concentration in the affected paws when administered GYY4137." (PMID 31551776, 2019).
heart failure (64 papers, 2013 to 2025). Inability of the heart to pump blood at an adequate rate to meet tissue metabolic requirements. "Patients with heart failure and cardiac dysfunction have higher levels of MPO, a marker of inflammation which is well-known to be linked to the severity of the disease." (PMID 40459761, 2025). "The major aspect why MPO suggests being superior to other markers of oxidative stress is that it is mechanistically linked to the development of heart failure." (PMID 32564144, 2021). "It has been reported that myeloperoxidase levels were linked to functional indices of worsening heart failure, similarly to what we observed for monocytes in our work." (PMID 33670636, 2021). "In heart failure patients, plasma MPO levels are elevated and associated with worse cardiac function, and have been reported to be a predictor of heart failure outcome." (PMID 31822739, 2019). "Higher MPO levels are associated with more advanced heart failure and adverse outcome in chronic heart failure patients." (PMID 26280875, 2016). "These inflammatory markers, i.e., elastase and myeloperoxidase, were found to be significantly higher in patients with heart failure, showing that inflammation is potentially associated with the pathogenesis of heart failure and increased mortality in such patients." (PMID 38592030, 2024). "In addition, elevated MPO is associated with increased incidence of heart failure and cardiovascular composite outcomes including MI in patients with CKD." (PMID 39472324, 2024). "Indeed, MPO levels are elevated in heart failure patients and associated with worse cardiac function." (PMID 38004170, 2023). "Research has elucidated a significant link between raised levels of MPO and an enhanced risk of ischemic stroke, with recent investigations also associating MPO with the onset of heart failure, a crucial contributing factor to the development of ischemic stroke." (PMID 38156091, 2023). "MPO is an inflammatory enzyme associated with obesity, hypertension, and heart failure, so its attenuation could have protective effects on multiple organs." (PMID 36142645, 2022). "Similarly, MPO is a key biomarker associated with atherosclerotic lesions and heart failure in the general population, as highlighted by the Framingham Heart Study and other population-based adult studies." (PMID 33066786, 2020). "Integrating MPO in risk stratification models could have an additional value in identifying patients at higher risk of developing heart failure, recurrent ischemia, and clinical events specially mortality." (PMID 31341419, 2019). "Among them, myeloperoxidase (MPO) has been investigated as a potential biomarker in heart failure, showing promising results for prognostic stratification." (PMID 40869365, 2025). "The SATELLITE trial (Safety and Tolerability Study of AZD4831 in Patients with Heart Failure) investigated the MPO inhibitor AZD4831 (Mitiperstat) in patients with heart failure." (PMID 40360833, 2025). "By encouraging the oxidation of sarcomeric protein and facilitating cardiac inflammation and apoptosis, MPO, a marker of inflammation, was reported to be elevated in patients with heart failure and cardiac dysfunction." (PMID 40459761, 2025). "MPO inhibitors are in clinical development for several cardiac indications, including heart failure with preserved ejection fraction (HFwPEF)." (PMID 38978787, 2024). "The elevated MPO levels in coronary circulation suggest localized tissue injury due to pathophysiological processes of cardiac failure." (PMID 39742176, 2024). "Excessive MPO release reportedly exacerbates oxidative stress, leading to various metabolic disorders and cardiovascular diseases, such as heart failure and myocardial ischemia." (PMID 37719981, 2023). "Oxidative modifications of sarcomeric proteins contribute to contractile dysfunction in heart failure patients and MPO has been shown to induce sarcomeric protein carbonylation in vitro." (PMID 37656254, 2023).
heart failure (continued). "Serum levels of myeloperoxidase, vitamin D3, ceruloplasmin, and 8-hydroxy-2-0-deoxyguanosine correlate well with the stage of heart failure." (PMID 35626917, 2022). "The role of MPO as a biomarker of heart failure has been supported by clinicopathological and epidemiological studies." (PMID 35419382, 2022). "Among the biomarkers, changes in myeloperoxidase (MPO) were related to outcomes in heart failure with preserved eject fraction patients." (PMID 36552578, 2022). "Increase in MPO blood levels was related with cardiovascular events in patients presenting with chest pain, as well as with the presence of heart failure in the general population." (PMID 35087624, 2022). "The fact that, in our analysis, MPO correlated with NT-proBNP, a strong parameter for structural remodeling in heart failure, implies that MPO levels decrease because of reverse remodeling under successful CRT." (PMID 32564144, 2021). "Previous studies with larger populations have shown that additional assessment of MPO to NT-proBNP was able to increase specificity in heart failure patients (74.1% vs. 40.5% with NT-proBNP alone)." (PMID 32564144, 2021). "In heart failure patients, MPO has an additive prognostic value over NT-proBNP testing, its principal prognostic value being in patients with intermediate NT-proBNP levels." (PMID 34073616, 2021). "Crude incidence rate and adjusted hazard ratios (HR) with 95% confidence intervals (95% CI) of incident heart failure in relation to monocyte myeloperoxidase median fluorescence intensity (MFI) tertiles, ARIC, 2005–2015." (PMID 30300402, 2018). "We here provide the first evidence that levosimendan treatment inhibits MPO release by PMNs in decompensated heart failure patients." (PMID 25867530, 2015). "Given the general state of neurohormonal activation which accompanies acute heart failure decompensation, the direct effects of levosimendan on MPO release and PMN activation have likely been under-recognised." (PMID 25867530, 2015). "Hypercoagulability mediated by leukocytes, especially neutrophils, and myocardial toxicity mediated by various inflammatory mediators and enzymes, such as elastase, myeloperoxidase, and acid phosphatase, contribute to adverse outcomes such as heart failure in patients with STEMI." (PMID 36200052, 2022). "MPO is used as an independent predictor of heart failure and cardiovascular events." (PMID 35626917, 2022). "Additionally, it has been shown that plasma MPO levels are elevated in patients with heart failure and also correlate with disease severity, as reflected by the positive relationship with NYHA functional class." (PMID 34073616, 2021). "Endothelial dysfunction as a mechanism of chronic heart failure progression could potentially lead to a refocusing on MPO as a therapeutical target for heart failure." (PMID 33916434, 2021). "Nevertheless, our data suggest that levosimendan has inhibitory effects on MPO release which might be beneficial for vascular endothelial function, contributing to blood pressure regulation in heart failure patients." (PMID 25867530, 2015). "Interestingly, patients with heart failure (HF) also have increased plasma MPO levels." (PMID 33916434, 2021). "The relationships of MPO and NGAL to heart disease have been described previously mainly for heart failure and coronary heart disease." (PMID 40940435, 2025). "In the SATELLITE trial, mitiperstat, an MPO inhibitor, was evaluated in patients with NYHA class II-IV symptoms, specifically HFpEF or heart failure with mildly reduced ejection fraction (HFmrEF)." (PMID 40528106, 2025). "Leukocyte contribution to ROS generation is suggested by the presence of myeloperoxidase (MPO) in plasma, correlating with heart failure severity." (PMID 39456418, 2024).